SMARCB1 (SWI/SNF related BAF chromatin remodeling complex subunit B1)
Diseases named in the same sentence as SMARCB1 in open-access papers (continued):
Sharing a sentence is not in itself a finding about the gene and the disease.
rhabdoid tumor (continued). "The prototypical example that illustrates such morphologic changes is malignant rhabdoid tumor, which is caused by SMARCB1 biallelic inactivation in virtually all cases." (PMID 35125107, 2022). "Some studies have demonstrated the efficacy of EZH2 and AURKA inhibitors in patients with rhabdoid tumors, also defined by the loss of SMARCB1." (PMID 35406448, 2022). "Broad inhibitors of tyrosine kinase receptors (RTKs), such as ponatinib, have been identified as SMARCB1-related therapies and particularly PDGFR and FGFR are expressed in rhabdoid tumors upon SMARCB1 loss." (PMID 35159116, 2022). "In approximately 35% of individuals diagnosed with an AT/RT or RTK, one of the SMARCB1 alterations is present in the germline, predisposing the individual to the development of rhabdoid tumors." (PMID 35912263, 2022). "Mutations of the SMARCB1 gene were described in other tumors, such as epithelioid sarcomas, and in myoepithelial carcinomas, and most importantly, in rhabdoid tumors (RTs)." (PMID 35200537, 2022). "SMARCB1 and SMARCA4 are tumor suppressor genes playing a critical etiologic role in all rhabdoid tumors including AT/RT, which is linked to somatic and germline mutations of SMARCB1 or, more rarely, SMARCA4." (PMID 33692948, 2021). "Most atypical teratoid/rhabdoid tumor (AT/RT) of the central nervous system shows an inactivation of SMARCB1 (INI1) and is considered as the hallmark of this neoplasm." (PMID 34611487, 2021). "Selinexor, a selective exportin-1 inhibitor, was effective in inhibiting the nuclear export of SMARCB1(Q318X) and caused rapid cell death in rhabdoid tumor cells." (PMID 34003336, 2021). "This study also described a SMARCB1 mutation in an extracranial malignant rhabdoid tumor (c.delG950) that caused cytoplasmic accumulation of truncated protein and loss of tumor suppressor function in vitro." (PMID 34003336, 2021). "Germline SMARCB1 mutations located in the central portion of the gene, involving multiple exon deletions or duplications and truncating mutations, likely responsible for a loss of SMARCB1 protein product, are most frequently associated with rhabdoid tumors." (PMID 33692948, 2021). "Atypical teratoid/rhabdoid tumors (AT/RTs) in the rhabdoid tumor predisposition syndromes are most often caused by germline mutations of the SMARCB1 gene located in chromosome 22q11.2." (PMID 34777208, 2021). "Loss of SMARCB1 (INI1, BAF47) is usually present in childhood malignant rhabdoid tumors (MRT), a rare but lethal pediatric sarcomas characterized by a 22q11 chromosome rearrangement." (PMID 34671561, 2021). "A case of a recurrent rhabdoid tumor with a mutation in the cell cycle inhibitor CDKN1C in addition to the hallmark biallelic loss of SMARCB1 has recently been reported." (PMID 33917833, 2021). "In contrast to extracranial malignant rhabdoid tumors, which characteristically show homozygous deletions affecting the SMARCB1 region, C-terminal truncating mutations are frequent in ATRT and predominantly encountered in the molecular subgroup ATRT-TYR." (PMID 34003336, 2021). "Rhabdoid tumors share germline and somatic mutations in SMARCB1 or, more rarely, SMARCA4, members of the SWI/SNF chromatin-remodeling complex." (PMID 33692948, 2021). "Inhibition of SMARCB1‐deficient SWI/SNF triggers an epigenetic switch to cause differentiation of rhabdoid tumor mouse xenografts into bone." (PMID 33332735, 2021). "A recent study of rhabdoid tumors detected SMARCB1-dependent (SWI/SNF related, matrix associated, actin dependent regulator of chromatin, subfamily B, member 1) re-expression of endogenous retroviruses (ERVs) along with interferon-signaling." (PMID 34945804, 2021).
rhabdoid tumor (continued). "Similar non-mutational SMARCA2 silencing has been also found in concomitant deficiency with SMARCB1 in malignant rhabdoid tumors." (PMID 34440689, 2021). "SMARCB1 deficiency was linked to malignant rhabdoid tumors and the literature reported gastric rhabdoid/undifferentiated carcinomas were associated with complete SMARCB1 absence." (PMID 33481850, 2021). "SWI/SNF chromatin remodellers were first linked to cancer development more than two decades ago when it was discovered that biallelic loss-of-function mutations of the SMARCB1 gene drive tumourigenesis in malignant rhabdoid tumours (MRTs)." (PMID 33941852, 2021). "The first SWI/SNF-associated cancer was identified in 1990s, which was a rare, highly aggressive cancer that hit young children known as Rhabdoid tumor, which has a mutation in the gene encoding the SMARCB1 subunit." (PMID 34440689, 2021). "SMARCB1 has been implicated in numerous other solid cancers as a tumor suppressor gene, including sarcomas, carcinomas and rhabdoid tumors of varying sites." (PMID 34051734, 2021). "Congenital cases have also been reported mainly in the context of rhabdoid tumor predisposition syndrome 1 or 2, associated with the germline mutation of SMARCB1 or SMARCA4, respectively." (PMID 33917833, 2021). "Inactivating mutation in SMARCB1/INI1 is an oncogene driver in rhabdoid tumors, and the loss of functional SMARCB1/INI1 leads to increase in ezrin expression." (PMID 32317857, 2020). "In human malignant rhabdoid tumors, loss of SMARCB1 (a subunit of SWI/SNF) leads to Polycomb-mediated repression of genes that suppress proliferation; when SMARCB1 is re-expressed, Polycomb is removed from the chromatin and DNA methylation is lost." (PMID 31259687, 2019). "SMARCB1 heterozygous germline mutations underlying tumor predisposition syndromes, the rhabdoid tumor predisposition syndrome 1 (RTPS1) and schwannomatosis, are in the vast majority of a different type." (PMID 31273213, 2019). "Complete loss of SMARCB1/SNF5 is very common in malignant rhabdoid tumors (MRT) and atypical teratoid/rhabdoid tumors (ATRT)." (PMID 31590683, 2019). "Almost all cases of ES are negative for ERG gene rearrangement and according to detection by IHC or fluorescence in situ hybridization (FISH), 90% of malignant rhabdoid tumors show nuclear deficiency of INI1, with the inactivation of SMARCB1." (PMID 31615564, 2019). "Specific SMARCB1 biallelic inactivating mutations were discovered in majority cases of malignant rhabdoid tumors (MRTs)." (PMID 29625594, 2018). "Loss of SMARCB1 protein expression has been reported to be associated with atypical teratoid/rhabdoid tumors and malignant rhabdoid tumors of the kidney and extrarenal tissues." (PMID 29625594, 2018). "Initially, SMARCB1 (SWI‐SNF‐related matrix‐associated actin‐dependent regulator of chromatin subfamily B member 1) was shown to be biallelically inactivated in malignant rhabdoid tumor cell lines." (PMID 30108113, 2018). "The SWI/SNF complex has been implicated in malignant rhabdoid tumors, and specific subunits of this complex (SNF5/SMARCB1, SMARCE1, BRG1, PBRM1/BAF180) have been identified in approximately 20% of human cancers including renal carcinoma, and NSCLC." (PMID 29988316, 2018). "Later, mutations and aberrant expression of SMARCB1 have been reported in various tumor types including familial schwannomas, melanomas, and rhabdoid tumors from different locations." (PMID 30108113, 2018). "Unopposed EZH2 activity is also a driver of cancers determined by the loss of the core subunit SNF5/SMARCB1 in the SWI/SNF complex as demonstrated in rhabdoid tumor, a highly malignant aggressive type of pediatric cancer." (PMID 30510924, 2018). "Loss of SMARCB1 expression has been reported to be associated with atypical teratoid / rhabdoid tumors (AT / RT) and malignant rhabdoid tumors (MRTs) of the kidney and extrarenal tissues." (PMID 29625594, 2018).
rhabdoid tumor (continued). "Epithelioid sarcoma and malignant rhabdoid tumor are 2 prototypical sarcoma types that are deficient in SMARCB1." (PMID 29625594, 2018). "Truncating forms of SMARCB1 are linked to an aggressive tumor phenotype, and are frequent in malignant rhabdoid tumors and epithelioid sarcomas, but rarely found in NSCLC." (PMID 30093964, 2018). "Rhabdoid tumors are caused by the deletion of SMARCB1, whose protein encodes the SMARCB1 subunit of the chromatin remodeling complex SWI/SNF that is involved in global chromatin organization and gene expression control." (PMID 29156698, 2017). "Here the authors present new mouse models and show that early Smarcb1 loss causes rhabdoid tumors whereas loss at later stages combined with Nf2 gene inactivation causes shwannomas." (PMID 28824165, 2017). "Extra-cranial rhabdoid tumors (RT) are highly aggressive malignancies of infancy, characterized by undifferentiated histological features and loss of SMARCB1 expression." (PMID 28427232, 2017). "This high mutational burden is in direct contrast with the genomic profile of rhabdoid tumor, a pediatric neoplasm also driven by the loss of SMARCB1; the mutation rate of epithelioid sarcoma is three orders of magnitude greater than that of rhabdoid tumor." (PMID 27732970, 2017). "The genetic hallmark of all rhabdoid tumors is the biallelic inactivation of SMARCB1 tumor suppressor gene." (PMID 28427232, 2017). "The definition of the “rhabdoid tumor” entity is confusedly based on the presence of a phenotype “compatible with this diagnosis” in a context of SMARCB1 bi-allelic inactivation and/or BAF47 loss of expression." (PMID 28427232, 2017). "Analysis of the SMARCB1 gene mutation spectrum points to genotype-phenotype correlations, with germline rhabdoid tumor mutations being more centrally placed in the coding sequence, involving multiple exons and truncating mutations of the SMARCB1 gene." (PMID 28824165, 2017). "Malignant rhabdoid tumors (MRTs) are lethal pediatric cancers characterized by a deficiency in the SWI/SNF subunit SMARCB1." (PMID 27783942, 2016). "The SWI/SNF complex has been linked to human cancer since the discovery that the SWI/SNF subunit BAF47 (SNF5, SMARCB1, INI1) was a bona fide tumor suppressor that underlies the genesis of malignant Rhabdoid tumors." (PMID 27486753, 2016). "Malignant rhabdoid tumors (MRTs) are pediatric cancers characterized by a deficiency in the SWI/SNF subunit SMARCB1." (PMID 27783942, 2016). "Up to one-third of patients with rhabdoid tumors have been found to have a genetic predisposition to these tumors secondary to a germline SMARCB1 alteration." (PMID 26064731, 2015). "More specifically, inactivating mutations of SMARCB1 are found in all Malignant Rhabdoid Tumors (MRT) and Atypical Teratoid/Rhabdoid Tumors (AT/RT), two highly aggressive forms of pediatric neoplasms." (PMID 26370283, 2015). "The INI1/hSNF5/SMARCB1 subunit is mutated in both malignant rhabdoid tumor, a highly aggressive childhood cancer, and schwannomatosis, a tumor-predisposing syndrome characterized by mostly benign tumors of the CNS." (PMID 26073604, 2015). "Mutations typically lead to loss of function, suggesting tumor suppressor roles of BAF complexes, in particular in childhood malignant rhabdoid tumors (loss of SMARCB1/SNF5) as well as ovarian and endometrial carcinomas (ARIAD1A)." (PMID 26702435, 2015). "Germline alterations in SMARCB1 give rise to the Rhabdoid Tumour Predisposition Syndrome (RTPS) which is manifested by development of malignant rhabdoid tumours in infancy and early childhood." (PMID 26998479, 2015). "We previously showed that re-introduction of Smarcb1 diminishes the oncogenic capacity of Smarcb1 deficient mouse rhabdoid tumors." (PMID 26370283, 2015).
rhabdoid tumor (continued). "More recently, WT EZH2 has emerged as a vulnerability in cancer associated with inactivation in the chromatin remodeling SWI/SNF complex, such as SMARCB1/INI1 mutated rhabdoid cancer and ARID1A mutated ovarian cancers." (PMID 26360609, 2015). "Mutation and inactivation of SMARCB1 have been identified as the underlying mechanism leading to Malignant Rhabdoid Tumors (MRT) and Atypical Teratoid/Rhabdoid Tumors (AT/RT), two highly aggressive forms of pediatric neoplasms." (PMID 26370283, 2015). "Sample 3-1 also harbored a non-synonymous mutation in SMARCB1, a gene that has been associated with congenital risk of rhabdoid tumors and chondrosarcomas." (PMID 25300797, 2014). "In 1990s, SMARCB1 mutations and the subsequent inactivation of SMARCB1 in rhabdoid tumors led to the realization that the SWI/SNF complex is often a target in cancer." (PMID 25774356, 2014). "Recently, flavopiridol has been shown to inhibit the growth of rhabdoid tumors, which are deficient in BAF47 (SMARCB1; INI1) and commonly deficient in BRM as well." (PMID 25774356, 2014). "Rhabdoid tumors seem to lack other mutations than those found in SMARCB1, suggesting epigenetic changes high likely in this tumor entity." (PMID 23764045, 2013). "Gene set enrichment analysis (GSEA) demonstrated that gene programs, which are deregulated by loss of SMARCB1 in rhabdoid tumors (MYC, cyclin D1 and the pluripotency program) are further upregulatedfollowing SAHA treatment." (PMID 23764045, 2013). "SNF5 is also known as a bona fide tumor suppressor based on genetic evidence that the majority of rhabdoid tumors contain bi-allelic inactivating mutations in the SNF5 (SMARCB1) locus." (PMID 23637628, 2013). "SMARCB1/INI1 germ-line mutations were first described in the malignant rhabdoid tumors (MRT) of infancy and atypical theratoid/rhabdoid tumors of the central nervous system and define a hereditary condition known as “Rhabdoid predisposition syndrome”." (PMID 24286138, 2013). "Malignant rhabdoid tumors (MRTs) are aggressive pediatric cancers arising in brain, kidney and soft tissues, which are characterized by loss of the tumor suppressor SNF5/SMARCB1." (PMID 24204904, 2013). "SMARCB1 acts as a tumor suppressor whose mutations or loss were shown to cause malignant rhabdoid tumors, an extremely aggressive cancer of early childhood and accumulation of DNA damage." (PMID 20706582, 2010). "Re-expression of SMARCB1 in human rhabdoid tumor cell lines causes G0/G1 arrest showing that restoration of SMARCB1 expression is sufficient to suppress proliferation." (PMID 19221586, 2009). "Germ-line SMARCB1 inactivation has been reported in association with rhabdoid tumor, epitheloid sarcoma and familial schwannomatosis, underscoring the importance of accurate mutation screening to ascertain recurrence and transmission risks." (PMID 20003390, 2009). "Overall nine distinct pathogenic SMARCB1 mutations were identified in a total of 19 possible rhabdoid tumors." (PMID 20003390, 2009). "While immuno-histochemical staining for SMARCB1 protein has greatly facilitated the diagnosis of rhabdoid tumor, identification of a mutation is necessary for the ascertainment of the germ-line mutational status." (PMID 20003390, 2009). "This is becoming increasingly relevant in line with reports of associations between SMARCB1 mutation and germ-line predisposition to both rhabdoid tumor and schwannoma, and is an important aspect of clinical management for these patients." (PMID 20003390, 2009). "Due to the high degree of dedifferentiation observed in SMARCA4-deficient undifferentiated RCC, these tumors are morphologically similar to SMARCB1-deficient malignant rhabdoid tumor (MRT), rhabdomyoblastic RCC, and other small round cell undifferentiated tumors, which can lead to misdiagnosis." (PMID 41312169, 2025). "However, resistance to tazemetostat in patient-derived SMARCB1-deficient epithelioid sarcomas or rhabdoid tumors has been observed." (PMID 40556679, 2025).
rhabdoid tumor (continued). "The study found that rhabdoid tumors (RT), which are highly aggressive due to the loss of the key tumor suppressor protein SMARCB1, could be suppressed by the depletion of the quality control protein DCAF5." (PMID 40115023, 2025). "Moreover, we used a published data set (GSE11482) to confirm that expression of KREMEN2 mRNA in kidney rhabdoid tumors, which are deficient in the SMARCB1 gene, was significantly higher than that in other types of kidney tumor." (PMID 38839769, 2024). "Biological relevance of this tumor suppressor gene was first highlighted in a murine model where loss of SMARCB1 was shown to result in a highly penetrant cancer predisposition with 100% of mice developing mature CD8+ T cell lymphoma or rare rhabdoid tumors with a median onset of 11 weeks." (PMID 39125735, 2024). "Small cell undifferentiated (SCU) histology and alpha-fetoprotein (AFP) levels below 100 ng/mL have been reported as poor prognostic factors in hepatoblastoma (HB); subsequent studies reported SMARCB1 mutations in some SCU HBs confirming the diagnosis of rhabdoid tumor." (PMID 36672416, 2023). "Known associations included NF1 in LGG and SMARCB1 in atypical teratoid/rhabdoid tumor (AT/RT)." (PMID 36928815, 2023). "Interestingly, the most specifically enriched motif for the P81S11/2 HA peak set was CTCF/BORIS, which has been linked to the formation of SMARCB1 mutant rhabdoid tumors and the maintenance of a naive pluripotent stem cell state." (PMID 37554444, 2023). "Similarly, almost all pediatric rhabdoid tumors exhibit loss of SWI/SNF core subunit SMARCB1, which encodes the subunit SNF5." (PMID 37415185, 2023). "This was first established in rhabdoid tumors bearing SMARCB1 loss-of-function mutations." (PMID 37094128, 2023). "Biallelic SMARCB1 mutations are frequently observed in malignant rhabdoid tumors (MRTs) and atypical teratoid rhabdoid tumors, which are aggressive and poorly differentiated pediatric tumors that occur predominately in the kidney or soft tissue and central nervous system, respectively." (PMID 37554444, 2023). "The synthetic lethal relationship was first identified in SMARCB1 deficient rhabdoid tumors and lymphomas, in which tumor phenotypes could be rescued by inhibition of EZH2." (PMID 35326450, 2022). "Almost 100% of rhabdoid tumors are defined by loss of SMARCB1 (SWI/SNF Related, Matrix Associated, Actin Dependent Regulator of Chromatin, Subfamily B, Member 1), a tumor suppressor gene that encodes the SNF5 subunit of the SWI/SNF (Switch/Sucrose Non-Fermentable) chromatin remodeling complex." (PMID 35650187, 2022). "Specifically, the core subunit SMARCB1 (INI1), is the most frequently inactivated subunit in mesenchymal neoplasms, with SMARCB1 deficiency being characteristic of malignant rhabdoid tumors (MRT), epithelioid sarcoma (ES), and most of poorly differentiated chordoma." (PMID 35327458, 2022). "This hypothesis is further supported by the observation that the re-expression of SMARCB1 in rhabdoid tumor cells leads to the upregulation of genes associated with the epithelial to mesenchymal transition." (PMID 35892904, 2022). "G401, G402 and A204 are malignant rhabdoid tumor (MRT) cells with SMARCB1 deficiency." (PMID 35169119, 2022). "In our study, the zebrafish embryo model of the rhabdoid tumor sample harboring the typical SMARCB1 deletion and a PRKCD (protein kinase C delta) mutation responded best to the EZH2 inhibitor tazemetostat and the multi-kinase inhibitor ponatinib out of 11 tested drug hits." (PMID 35159116, 2022). "Approximately one-third of patients with rhabdoid tumors have germline variants in SMARCB1." (PMID 36295546, 2022). "Among these, the core subunit SMARCB1 is the most frequently mutated, and SMARCB1 loss represents a founder driver event in several malignancies, such as malignant rhabdoid tumors (MRT), epithelioid sarcoma, poorly differentiated chordoma, and renal medullary carcinoma (RMC)." (PMID 35327458, 2022).